F11 (coagulation factor XI)
Description:
Factor XI triggers the middle phase of the intrinsic pathway of blood coagulation by activating factor IX.
Synonyms: FXI; PTA
Tractability: Small molecule: a drug acting on it is in phase 2 or 3 trials; a structure with a bound ligand is known; a high-quality ligand is known; it has a binding pocket of medium quality; it belongs to a druggable protein family. Antibody: a drug acting on it is in phase 2 or 3 trials; its Gene Ontology location is reachable by antibodies, with high confidence; UniProt places it where antibodies can reach, with medium confidence; UniProt predicts a signal peptide or a membrane-spanning region. PROTAC: its protein half-life has been measured; a small molecule that binds it is known. Other modalities: an approved drug acts on it.
Target class: Serine protease; Enzyme; Serine protease PA clan; Serine protease S1A subfamily; Protease
Chemical probes: MILVEXIAN
Safety:
Unwanted effects reported when the protein is acted on. In parentheses: how it was acted on, where the effect was seen, and who reports it.
venous thrombosis (source: ClinPGx)
Gene: Protein-coding gene on chromosome 4 (186,260,159 to 186,291,273, forward strand). Ensembl gene ENSG00000088926.
Subcellular location: Secreted
Subcellular location (Human Protein Atlas): Vesicles; Predicted to be secreted
Pathways (Reactome):
Hemostasis: Amplification and propagation of coagulation cascade; FXIIa, PKa-dependent activation of coagulation pathway; Regulation of clotting cascade
Disease: Defective F9 activation
Gene Ontology:
Molecular function: protein binding; serine-type endopeptidase activity; serine-type peptidase activity; serine-type aminopeptidase activity
Biological process: blood coagulation; plasminogen activation; positive regulation of fibrinolysis; proteolysis
Cellular component: extracellular exosome; extracellular region; membrane; plasma membrane
Genetic constraint (gnomAD): Loss-of-function variants: 68 observed, 72.65 expected, observed/expected ratio (o/e) 0.94, 90% interval 0.77 to 1.14. The upper end of that interval is the gene's LOEUF score, 1.14, which puts it in group 5 of 6, group 1 being the genes least tolerant of losing a copy. Missense variants: 706 observed, 770.48 expected, observed/expected ratio (o/e) 0.92, 90% interval 0.86 to 0.98. Synonymous variants: 264 observed, 279.1 expected, observed/expected ratio (o/e) 0.95, 90% interval 0.86 to 1.05.
Gene-disease validity (ClinGen):
ClinGen rates the evidence that F11 causes each of these diseases.
congenital factor XI deficiency (semidominant): Definitive. Congenital factor XI deficiency is an inherited bleeding disorder characterized by reduced levels and activity of factor XI (FXI) resulting in moderate bleeding symptoms, usually occurring after trauma or surgery.
Homologues: Orthologues: chimpanzee F11 (99% identical), macaque F11 (96% identical), dog F11 (86% identical), pig F11 (86% identical), rabbit F11 (86% identical), guinea pig F11 (83% identical), mouse F11 (78% identical), rat F11 (73% identical), tropical clawed frog klkb1 (48% identical). Paralogues in human: KLKB1 (58% identical), F12 (21% identical), HGFAC (21% identical), C1R (20% identical), C1S (19% identical), CFI (19% identical), F7 (19% identical), F10 (18% identical), F9 (17% identical), PRSS55 (17% identical), C1RL (14% identical), PRSS51 (13% identical), and 4 more.
Diseases named in the same sentence as F11 in open-access papers:
F11 is named in the same sentence as 97 diseases in open-access papers, as found by Europe PMC text mining. Sharing a sentence is not in itself a finding about the gene and the disease. The quoted sentences say what the papers report.
thrombosis (33 papers, 2013 to 2026). "Similarly, genetic variation in F11 was also associated with both deep vein thrombosis and the level of coagulation factor XI." (PMID 35449099, 2022). "Single nucleotide polymorphisms (SNPs) in a 4q35.2 locus that harbors the coagulation factor XI (F11), prekallikrein (KLKB1), and a cytochrome P450 family member (CYP4V2) genes are associated with deep venous thrombosis (DVT)." (PMID 24066149, 2013). "Also, significant genetic variants were found in fibrinogen and coagulation factor XI, which are crucial in the coagulation cascade, as well as a significant genetic overlap between CTEPH and patients with PE or deep vein thrombosis (DVT)." (PMID 39997467, 2025).
ischemic stroke (24 papers, 2013 to 2026). A stroke disorder caused by obstruction of blood flow to the brain, due to thrombotic (local blood clot formation) or embolic (due to a blood clot or other material traveling from another site) event. "The aim of our study was to investigate whether FXI gene (F11) variants are associated with ischemic stroke." (PMID 24086496, 2013). "APOL3, LRP4, and F11, on the other hand, have specific effects on cardiomyopathy and ischemic stroke, respectively, all classified as highly recommended level protein targets." (PMID 38820305, 2024). "APOL3, LRP4, and F11, on the other hand, have specific effects on cardiomyopathy and ischemic stroke, respectively." (PMID 38820305, 2024). "Although the exact functional consequences of F11 rs4253417 and HIVEP1 rs169713 remain unclear, F11 encodes coagulation factor XI, suggesting that variants in this gene may influence plasma FXI levels and modulate thrombosis risk, as previously identified in patients with ischemic stroke." (PMID 41440514, 2025). "We found that fat mass independently increased plasma levels of all protein mediators (COL6A3-derived endotrophin, F11, PCSK9, C1R and SPATA20) and increased the odds of type 2 diabetes, CAD and ischemic stroke." (PMID 39856218, 2025).
hemophilia C (19 papers, 2014 to 2025). "Factor XI (FXI) deficiency, or hemophilia C, is a rare bleeding disorder resulting from reduced levels or dysfunctional FXI protein due to mutations in the F11 gene." (PMID 41009375, 2025).
Stroke (15 papers, 2017 to 2026). Sudden impairment of blood flow to a part of the brain due to occlusion or rupture of an artery to the brain. "The PWAS identified 7 genes (MMP12, F11, ENGASE, SH3BGRL3, SPATA20, SWAP70, SCARA5) whose cis-regulated plasma protein levels were associated with stroke and its subtypes at a FDR of P < 0.05." (PMID 41488603, 2026). "We identified 7 potential risk genes (MMP12, F11, SH3BGRL3, ENGASE, SCARA5, SWAP70 and SPATA20) of stroke with altered protein abundances in the plasma." (PMID 41488603, 2026). "In blood, we identified 5 genes (MMP12, SCARF1, ABO, F11, and CKAP2) that had causal relationships with stroke and stroke subtypes." (PMID 35449099, 2022). "We found that the protein abundance of seven genes (MMP12, F11, SH3BGRL3, ENGASE, SCARA5, SWAP70 and SPATA20) in the plasma was associated with stroke and its subtypes, and six genes (MMP12, F11, SH3BGRL3, SCARA5, SWAP70 and SPATA20) causally related with stroke and its subtypes." (PMID 41488603, 2026). "Finally, MR has provided support for a novel drug target to be used for stroke prevention: the coagulation factor XI (FXI)." (PMID 38261980, 2024). "Eight protein-disease pairs were ranked as the most valuable findings after the filtering, which include IL-7R and TNFSF12 level on asthma; ACE level on COPD; AIF1 level on HF; SERPINF1 level on stroke; and SERPINE2, F11, KLKB1, and ABO level on VTE." (PMID 36388766, 2022). "Furthermore, 5 different genes (MMP12, ABO, SCARF1, F11, and CKAP2) were discovered in blood, which indicated two distinct pathogenesis for stroke in brain and blood." (PMID 35449099, 2022). "Using public drug databases, we curated drugs targeting those proteins in a direction compatible with a beneficial therapeutic effect against stroke based on MR estimates and identified such drugs for VCAM1, F11, KLKB1, GP1BA, LAMC2 (inhibitors) and PROC (activators)." (PMID 36180795, 2022).
bleeding disorder (13 papers, 2014 to 2026). "Acquired inhibitors of coagulation factor XI (FXI) are a rare cause of bleeding disorders, typically associated with autoimmune diseases or malignancies." (PMID 40655905, 2025). "While this is the first report of a F11 variant in FXI-deficient cats, F11 insertions associated with bleeding disorders due to FXI deficiency have been reported in cattle and dogs." (PMID 35627175, 2022).
COVID-19 (8 papers, 2020 to 2025). A disease caused by infection with severe acute respiratory syndrome coronavirus 2. "According to these criteria, we found four procoagulants (ADAMTS13, F11, HGFAC, KLKB1) and two anticoagulants (C1QTNF1, SERPINA5), whose expression may predispose males and older individuals to COVID-19-related coagulopathy and severe COVID-19 disease." (PMID 32751741, 2020). "In the protein combination, 4 proteins including F11, F9, FGA and FGG are involved in the blood coagulation cascade, and all of them were higher expressed in COVID-19-children than those in healthy children or COVID-19-adults." (PMID 34335977, 2021).
thrombotic disease (7 papers, 2013 to 2023). The formation of a blood clot in the lumen of a vessel or heart chamber; causes include coagulation disorders and vascular endothelial injury. "Specifically, plasma coagulation Factor XI (FXI) levels were considered as an intermediate quantitative phenotype in the Spanish families included in the Genetic Analysis of Idiopathic Thrombophilia 1 (GAIT-1) Project to identify new genetic risk factors that contribute to thrombotic disease." (PMID 28445521, 2017).
Hypertension (5 papers, 2019 to 2025). The presence of chronic increased pressure in the systemic arterial system. "Activated monocytes interact with platelet glycoprotein Ibα (GPIbα) and coagulation factor XI (FXI) to promote local thrombin generation, thereby exacerbating vascular inflammation and hypertension, and accelerating AAD progression." (PMID 41035635, 2025). "We found that monocyte activation and platelet receptor glycoprotein Ib alpha (GPIbα) participate in a local thrombin amplification, though coagulation factor XI (FXI), promoting the development of vascular inflammation and hypertension." (PMID 32664652, 2020). "Activated monocytes and platelet receptor glycoprotein Ib alpha (GPIbα) participate in local thrombin amplification through coagulation factor XI (FXI), thereby promoting the development of vascular inflammation and hypertension and accelerating the progression of AD." (PMID 37958896, 2023).
thrombophilia (5 papers, 2019 to 2025). A condition characterized by an abnormally high level of thrombi. "Genetic variations in the F11 gene have also been implicated in altered FXI activity, further supporting its role in thrombophilia." (PMID 40429442, 2025).
Menorrhagia (3 papers, 2023 to 2024). Prolonged and excessive menses at regular intervals in excess of 80 mL or lasting longer than 7 days. "Thus, detecting FXI plasma levels and analyzing the F11 gene in patients with abnormal bleeding after surgery or trauma, as well as menorrhagia, is of great value in clinical diagnosis." (PMID 38835089, 2024).
Alzheimer disease (2 papers, 2024). A progressive, neurodegenerative disease characterized by loss of function and death of nerve cells in several areas of the brain leading to loss of cognitive function such as memory and language. "In the DisGeNET database, LRP6, F11, CXCL10, TCF4 and IGF2 are identified as the top five genes associated with Alzheimer's disease, with association scores of 0.989, 0.981, 0.953, 0.938 and 0.914, respectively." (PMID 38350848, 2024).
autoimmune disease (1 paper, 2025). A disorder resulting from loss of function or tissue destruction of an organ or multiple organs, arising from humoral or cellular immune responses of the individual to their own tissue constituents. "The development of acquired inhibitors of coagulation factor XI (FXI) in patients without congenital deficiency is an extremely rare phenomenon and has been reported mostly in patients with autoimmune diseases or in association with malignancies." (PMID 40655905, 2025).
autoimmune hepatitis (1 paper, 2022). Hepatitis caused by autoantibodies. "We also described extra hematological autoimmunity, such as autoimmune nephrotic syndrome, autoimmune hepatitis, and abnormal coagulation assays due to coagulation factor XI autoantibodies." (PMID 36405754, 2022).
familial hypertrophic cardiomyopathy (1 paper, 2013). Hypertrophic cardiomyopathy caused by mutations in the genes encoding components of the sarcomere, in the absence of predisposing conditions. "Specifically SLC25A4 is connected with progressive external ophthalmoplegia and familial hypertrophic cardiomyopathy, TLR-3 with susceptibility or resistance to some kinds of infections, F11 with deficiency in coagulation factor XI and CYP4V2 with Bietti crystalline corneoretinal dystrophy." (PMID 24176130, 2013).
glioma (1 paper, 2020). A benign or malignant brain and spinal cord tumor that arises from glial cells (astrocytes, oligodendrocytes, ependymal cells). "Additionally, six targets are regulated by our miRNAs both in glioma and meningioma: CR2, KNG1, PROS1, F9, MBL2 and F11, while different miRNAs are dysregulated in each cancer type." (PMID 32545233, 2020).
Hearing impairment (1 paper, 2021). A decreased magnitude of the sensory perception of sound. "To date, F11, MTNR1A, and ZFP42 have not been associated with hearing impairment or inner ear anomalies." (PMID 33418956, 2021).
hepatocellular carcinoma (1 paper, 2022). A malignant tumor that arises from hepatocytes. "Interestingly, we found long-term survival of HBV leads to down-regulated expression levels of F11 and FBP1 mRNAs but up-regulated PSRC1 mRNA in HBV-replicating hepatocellular carcinoma cell lines." (PMID 36212461, 2022).
hyperhomocysteinemia (1 paper, 2020). A serious metabolic condition caused by mutations in the MTHFR gene, medications, or nutritional deficiency. "Taken together, our results suggest that severe hyperhomocysteinemia with or without hypermethioninemia disrupts production of liver-synthesized coagulation factor XI in a I278T mouse model of HCU." (PMID 32722248, 2020).
liver disease (1 paper, 2024). "By training random forest models, a biomarker panel comprising KNG1, F11, KLKB1, CAPNS1, CDH1, CPN2, NME2, was identified by feature selection for liver disease detection." (PMID 39207047, 2024).
virus infection (1 paper, 2024). "For instance, one study linked prolonged APTT in severe fever with thrombocytopenia syndrome (SFTS) to a deficiency in coagulation factor XI caused by SFTS virus infection." (PMID 39995828, 2024).
infection (5 papers, 2009 to 2025). The state of being infected such as from the introduction of a foreign agent such as serum, vaccine, antigenic substance or organism. "The loss of F11 or its ability to bind RhoA did however result in significantly higher levels of GTP bound RhoA at 8 hours post infection, consistent with the presence of actin stress fibres in ΔF11L or F11-VK as compared to WR or WR-A36R-YdF infected cells." (PMID 20041165, 2009). "We previously found that RhoA is inactivated by the GAP activity of myosin-9A, in an F11-dependent manner in late stages of infection." (PMID 28486133, 2017). "We now demonstrate that the vaccinia virus protein F11, which localizes to the plasma membrane, is required for ROCK-mediated cell contraction from 2 hr post infection." (PMID 28486133, 2017). "Several other genes such as P fimbrial adhesins, F11, Curli fimbriae, and other adhesins possess adhesion properties; these are commonly found in APEC isolated from septicemic cases, and play a pivotal role in stabilizing APEC infection." (PMID 32059459, 2020). "In contrast, HeLa cells infected with the recombinant ΔF11L virus, which does not express F11, have significantly more actin stress fibres than those infected with WR or A36R-YdF at 8 hours post-infection." (PMID 20041165, 2009).
tumor (3 papers, 2022 to 2025). "Moreover, we validated the differential expression of four model genes (CYS2, F11, ANXA10, and SLC22A1) between normal and tumor tissues in the GSE25097 and TCGA datasets." (PMID 39548390, 2024). "Furthermore, we validated the differential expression of the top five genes (C6, UGT2B7, SLC22A1, F11, and CYP2C8) between normal and tumor tissues using the GSE25097 and TCGA datasets." (PMID 39548390, 2024). "Therefore, the downregulation of F13A1 in SCLC is surprising, but may indicate a novel tumor suppressing role of blood coagulation in SCLC pathogenesis, which is supported by the similar downregulated expression of F11 in SCLC patients in the current study." (PMID 34996345, 2022).
F11 also shares sentences with these, for which no sentence is quoted: venous thromboembolism (21 papers); cancer (15); Thromboembolism (10); myocardial infarction (9); Sepsis (9); hemophilia A (6); Arterial thrombosis (5); atrial fibrillation (5); coagulopathy (5); deficiency (4); cardioembolic stroke (3); heart failure (3); hemorrhagic stroke (3); acute coronary syndrome (2); antiphospholipid antibody syndrome (2); atherosclerosis (2); bacterial infection (2); bacterial pneumonia (2); bacterial sepsis (2); diabetes (2); end-stage renal disease (2); factor deficiency (2); factor XI deficiency (2); hemorrhage (2); pneumonia (2); Renal insufficiency (2); Streptococcus pneumonia (2); systemic lupus erythematosus (2); Von Willebrand disease (2); abscess (1).
A further 45 diseases each share a sentence with F11 in 1 paper.